IL6 (interleukin 6)
Diseases named in the same sentence as IL6 in open-access papers (continued):
Sharing a sentence is not in itself a finding about the gene and the disease.
lactic acidosis (12 papers, 2013 to 2025). Metabolic acidosis characterized by the accumulation of lactate in the body. "Pro-inflammatory responses to hyperchloremic metabolic acidosis are mediated by nitric oxide and are associated with a higher interleukin (IL)-6 to IL-10 ratio when compared with lactic acidosis, as reported in in vitro cell models." (PMID 27716363, 2016). "M1 microglia produce pro-inflammatory cytokines such as IL-1β, TNF-α, and IL-6, which trigger the inflammatory response and cause damage such as mitochondrial oxidative phosphorylation, lactic acidosis, and excessive accumulation of free radicals, leading to neuronal necrosis." (PMID 40944219, 2025). "Systemic inflammatory markers (e.g., C-reactive protein (CRP), pro-inflammatory cytokine, Interleukin-6 (IL-6), and lactic acidosis frequently indicate systemic involvement and intestinal ischemia." (PMID 41007847, 2025). "The acADSC treatment with 10 ng/mL TGFβ1 was able to stimulate IL1B and IL6 gene expression at a similar level to lactic acidosis." (PMID 36980280, 2023). "In an animal model of metformin-associated lactic acidosis in CKD, it was shown that the administration of roxadustat or REC2923 was associated with a decrease in the expression of the proinflammatory cytokine, interleukin 6 (IL-6)." (PMID 39648258, 2025). "Viewed together these results imply that synergism between Ca2+ and low pH may be required to explain the regulation of IL‐6 mRNA under conditions relevant to lactic acidosis in exercise." (PMID 35141477, 2022). "It has previously been proposed that lactic acidosis following exercise promotes this IL‐6 up‐regulation, but the mechanism of this acidosis effect is unknown." (PMID 35141477, 2022). "However, whether such receptors are expressed in skeletal muscle (albeit transiently during exercise), and whether they play a role in sensing of lactic acidosis and in regulating IL‐6 expression in exercising skeletal muscle, remains to be determined." (PMID 35141477, 2022). "Exercise sufficient to deplete glycogen and increase glycolytic flux in muscle is necessary to elicit a strong IL‐6 response, and it has been proposed that the lactic acidosis resulting from such exercise may be an important contributor to this IL‐6 up‐regulation." (PMID 35141477, 2022). "Changes of plasma levels of TNF-α, IL-6, troponin-I, ALT, AST and urea following severe lactic acidosis in pigs." (PMID 23326542, 2013). "In the absence of stimulation, FACS-sorted day 3 LA-Mφ with and without depolarized mitochondria had similar levels of IL-6 and TNFα mRNA, higher in both cases than those in Mφ not exposed to lactic acidosis." (PMID 34880237, 2021).
Lipedema (12 papers, 2020 to 2025). Disorder of adipose tissue characterized by symmetric and bilateral enlargement of the lower extremities due to abnormal deposition of subcutaneous fat often in obese women. "The authors suggest, therefore, that the leg index, abdominal index, trunk index, and total index, combined with genetic analysis of the IL-6 gene polymorphism (rs1800795), can be used as promising clinical tools to diagnose the phenotype of lipedema and predict the evolution of the disease." (PMID 38958868, 2024). "Following the intervention diet, reduction in CRP (−0.39, p = 0.016) and IL-6 levels (−0.33, p = 0.034) in lipedema were observed." (PMID 41010539, 2025). "A significant positive association was observed between the intervention diet’s DII and CRP (r = 0.55, p = 0.005), and between the baseline diet’s DII and IL-6 (r = 0.50, p = 0.013) in lipedema group." (PMID 41010539, 2025). "The proinflammatory interleukin-1 pathway has been shown to be the most prominent downregulated pathway in lipedema macrophages and is accompanied by an altered interleukin-6 pathway, which is responsible for the alternative activation of macrophages." (PMID 36605202, 2022). "A trend of elevated expression of VEGF, IL-6, IL-1ß, and TNFα in differentiated lipedema adipocytes compared to controls was observed by Al-Ghadban, principally in adipose tissue derived from the thigh but not abdomen of donors." (PMID 36675759, 2022). "The data show an up-regulation of interleukin (IL)-6 gene expression in both lipedema ASCs (2-fold increase, p = 0.25) and adipocyte-differentiated spheroids (~1.8-fold increase, p = 0.23) compared to healthy spheroids." (PMID 33171717, 2020). "This study examined the complex genetic interactions related to body fat accumulation in patients with lipedema and found significant differences in fat distribution in women carrying or not carrying the IL-6 gene polymorphism (rs1800795)." (PMID 38958868, 2024). "Elevated levels of IL-6 and CRP in the blood indicate activation of the inflammatory response and are commonly observed in chronic diseases, as well as in lipedema." (PMID 41010539, 2025). "By analogy, in lipedema, a SAT phenotype genetically primed to overexpress IL-6 and to develop microangiopathy and adiposopathy may favour, and be particularly vulnerable to, a pro-inflammatory, endotoxemia-prone GM configuration." (PMID 41470854, 2025). "A significant decrease of IL-8 but not IL-6, IL-1ß or TNFα was found in supernatants from lipedema SVFs." (PMID 36675759, 2022). "In contrast, no changes in plasma levels of IL-6 were found in lipedema compared to BMI-matched controls." (PMID 36387874, 2022).
morbid obesity (12 papers, 2015 to 2025). An excess of body weight, normally defined as an individual with a body mass index greater than 35 or a body weight greater than one hundred percent of ideal body weight. "Previous studies have shown positive correlations between serum IL6 and BMI in patients with morbid obesity." (PMID 38667300, 2024). "In 70 Brazilian women with morbid obesity, the effect of genotype on the concentration of IL-6 but not TNF-α in the postprandial period was confirmed." (PMID 37626800, 2023). "While mouse models with deficient IL-6 signaling show an ameliorated but not absent Diethylnitrosamine (DEN)-induced HCC development, the morbid obesity in mice with mutant leptin signaling complicates the dissection of hepatic leptin receptor (LEPR) and IL-6 signaling in HCC development." (PMID 30224299, 2018).
myeloproliferative neoplasm (12 papers, 2013 to 2025). A clonal hematopoietic stem cell disorder, characterized by proliferation in the bone marrow of one or more of the myeloid (i.e., granulocytic, erythroid, megakaryocytic, and mast cell) lineages. "IL-6 has been implicated as a critical activator of myelopoiesis in response to chronic inflammatory disorders, including myeloproliferative neoplasm (MPN)." (PMID 26491227, 2015). "These mice exhibit lymphoproliferative and myeloproliferative disorders and have high circulating levels of IL-6." (PMID 26317211, 2015). "This study speaks to a molecular pathway involving miR-146a/TRAF6/NF-κB/IL-6 that links chronic inflammatory stresses to the functional decline and depletion of HSCs and the development of myeloproliferative diseases." (PMID 23705069, 2013). "Chronically, these nominal stressors can lead to severe pathologies, such as HSC exhaustion, bone marrow failure, and myeloproliferative disease, produced by chronic NF-κB hyperactivation and IL-6 overproduction." (PMID 23705069, 2013). "To determine whether IL-6 is a culprit gene downstream of NF-κB-mediating HSC depletion and myeloproliferative disease, we bred miR-146a KO mice with mice knocked out for the Il6 gene." (PMID 23705069, 2013). "Key to Rux efficacy is its broad anti-inflammatory activity against the myeloproliferative neoplasm (MPN) inherent cytokine storm with pro-inflammatory IL-1, IL-6, IL-8, IL-12, TNF-α, IFNγ, VEGF, TGFβ, FGF, PDGF, GM-CSF, and G-CSF cytokines/growth factors." (PMID 32518419, 2020). "Hepcidin levels are also regulated by inflammatory cytokines, such as IL-6; IL-6 regulates the expression of hepcidin via the JAK-STAT3 pathway, which is hyperactivated in myeloproliferative neoplasms (MPNs) and contributes to the increased hepcidin levels detected in primary MF patients." (PMID 38201581, 2023). "In addition, JAK2 is the overlapping gene, and disregulation of the IL6/JAK2/STAT3 signalling pathways can lead to increased cellular proliferation and myeloproliferative neoplasms of hematopoietic stem cells." (PMID 33126852, 2020). "Monoclonal antibodies and small inhibitory molecules targeting the IL-6/JAK/STAT3 pathway, including agents that interfere with IL-6 and its receptor or JAKs, have already received FDA approval for the treatment of inflammatory conditions or myeloproliferative neoplasms." (PMID 37237509, 2023).
paroxysmal AF (12 papers, 2014 to 2025). "It has been demonstrated that colchicine is an effective and safe agent for preventing early AF recurrences after pulmonary vein isolation in patients with paroxysmal AF, associated with reduced CRP and IL-6 levels." (PMID 30185438, 2018). "Patients with paroxysmal AF had a lower heart rate, a lower diastolic blood pressure, lower levels of IL-6 and NT-proBNP and a higher eGFR." (PMID 27701468, 2016). "Plasma markers (von Willebrand factor (vWf), soluble P-selectin (sPsel) and interleukin-6 (IL-6)) were measured by ELISA at three time points in 80 patients (62±10 years, 63% males, 41% paroxysmal AF) undergoing CA." (PMID 25390649, 2014). "In addition, patients with paroxysmal AF with the minor allele of SNPrs2106261 (TT + TC) had lower levels of C reactive protein(CRP), neutrophil/lymphocyte (N/L) ratios, and interleukin 6 (IL-6) expressionthan patients with the CC type." (PMID 39076272, 2023). "Few inflammatory markers including IL-6 and Hs-CRP correlate well with the presence of AF, and therefore have a potential clinical utility in AF prediction in patients with RHD, especially paroxysmal AF." (PMID 32923332, 2020).
perinatal asphyxia (12 papers, 2014 to 2024). A disorder caused by a lack of blood flow or gas exchange to or from the fetus in the period immediately before, during, or after the birth process. "It was concluded that IL6 measurement in the umbilical cord blood ofnewborns with perinatal asphyxia may be useful in early detection of neonateswith high risk of brain damage and adverse outcomes." (PMID 31435616, 2019). "Neurologic evaluation of 14 infants with perinatal asphyxia and 12healthy ones at 18 months of age revealed that 8 infants with perinatal asphyxiahad abnormal findings that were associated with serum levels of IL6 andIL-1β in 24 hr after birth." (PMID 31435616, 2019). "The current study aimed to evaluate the prognostic value of interleukin-6 (IL-6) and hypoxic-ischemic encephalopathy grade in the prediction of mortality and the developmental status of neonates affected by prenatal asphyxia." (PMID 34282369, 2021). "We, in a former study, have reported sensitivity and specificity of 80.5% and 81.6%, respectively, for IL-6; and 71% and 89.1%, respectively, for IL-1β, in diagnosis of perinatal asphyxia." (PMID 33680378, 2020). "Combination of IL6 and IL-1β at birth was studied in 38 infectious infantswith perinatal asphyxia (pH < 7.2, low Apgar score, and fetal distresssymptoms) and 47 healthy infants." (PMID 31435616, 2019). "Simultaneous assessment ofIL-1β and IL6 improved the sensitivity and specificity ofearly diagnosis of perinatal asphyxia." (PMID 31435616, 2019). "IL-1β and IL6 levels have been reported to besignificantly higher in infants with perinatal asphyxia compared to the controlgroup in 24 hr after birth." (PMID 31435616, 2019). "IL6 and IL-1β of serum samples were used in the earlydiagnosis of perinatal asphyxia and are useful predictors for the outcomes ofperinatal asphyxia and its intensity." (PMID 31435616, 2019). "The turning points forIL6 and IL-1β were 11.91 pb/ml and 3.35 pb/ml, respectively.The researchers concluded that simultaneous assessment of IL6 andIL-1β can improve the sensitivity and specificity forearly diagnosis of perinatal asphyxia." (PMID 31435616, 2019). "Studies have shown that elevated levels of IL-6, IL-10, and TNF-α in cerebrospinal fluid (CSF) may be associated with brain injury in both neonatal hypoxic-ischemic encephalopathy (HIE) and preterm infants with MRI-defined brain white matter injury." (PMID 38494527, 2024). "According to the logistic regression analysis, UCB IL-6, NT-proBNP, pH value, Apgar scores at 1 and 5 min, perinatal asphyxia, initial FiO2, invasive ventilation, surfactant therapy, HsPDA, RF, and IVH were identified as independent risk factors for grading BPD." (PMID 38161441, 2023). "Hence, the current study aimed to evaluate the prognostic value of interleukin-6 (IL-6) and hypoxic-ischemic encephalopathy grade in the prediction of mortality and developmental status of neonates affected by prenatal asphyxia." (PMID 34282369, 2021). "In addition, simultaneous evaluation ofIL-1β and IL6 can improve the sensitivity of theearly diagnosis of perinatal asphyxia." (PMID 31435616, 2019). "Therefore,combination of IL6 and IL-1β can be used as a potential substantially powerfulmarker for early diagnosis of perinatal asphyxia." (PMID 31435616, 2019). "Our ROC curve analyses showed that IL-6 and FasL in the CSF may be useful as additional tools for evaluating the severity of hypoxic-ischemic encephalopathy in post-asphyxiated infants and for predicting the long-term outcomes." (PMID 30089504, 2018). "This cohort study assessed whether Fas-ligand (FasL) and interleukin (IL)-6 levels in the cerebrospinal fluid (CSF) after hypoxic-ischemic encephalopathy (HIE) can serve as biomarkers of hypoxic brain injury in neonates." (PMID 30089504, 2018).
perinatal asphyxia (continued). "We hypothesized that FasL and IL-6 are upregulated in CSF samples from human infants after perinatal asphyxia and that they may correlate positively with the severity of HIE and the clinical outcome of patients." (PMID 30089504, 2018). "Indeed, a study of blood and CSF obtained during the first 24 h of life from infants who suffered hypoxic ischemic encephalopathy showed an increase in IL-1β, IL-6, and TNF-α levels, compared to control infants." (PMID 24723845, 2014). "Post-perinatal asphyxia CSF levels of IL-6 were correlated with the severity of infantile HIE, cerebral injury, and neurologic complications." (PMID 33680378, 2020). "To determine how well FasL and IL-6 predict HIE, we also assessed the ability of cord blood pH, which is the established biomarker for perinatal asphyxia, to predict HIE." (PMID 30089504, 2018). "A relationship between serum levels of IL-1β, IL-6, and TNF-α and the outcome of infants that have suffered of perinatal asphyxia has been observed in humans, suggesting that proinflammatory cytokines have a predictive value." (PMID 24723845, 2014). "A population-based survey found that the level of IL-6 in cerebrospinal fluid after perinatal asphyxia correlated with the severity of neonatal hypoxic-ischemic encephalopathy (HIE), brain injury and neurological outcome, suggesting a role for IL-6 in neonatal hypoxic-ischemic brain injury." (PMID 34759794, 2021).
postpartum depression (12 papers, 2016 to 2025). A type of clinical depression that occurs after childbirth. "Mangiferin treatment suppresses microglial activity and downregulates the levels of TNF-α, IL-6, and IL-1β in the hippocampus of mice with postpartum depression." (PMID 38915473, 2024). "Hypericin, one of the rich compounds in CS extract, has been reported to be able to alleviate the symptoms of postpartum depression as effective as fluoxetine by decreasing the levels of inflammatory factors (IL-6, IL-1β, TNF - α) in serum." (PMID 36909192, 2023). "It is worth emphasizing that the serum proinflammatory cytokines, including IL-1β and IL-6, were also increased in the rats with postpartum depression." (PMID 30390665, 2018). "The relationship persists after adjustment for potential confounders such as age, sex, ethnicity, SES, and psychological and behavioural problems preceding the measurement of IL-6, BMI and maternal postnatal depression." (PMID 27476619, 2017). "The biosignature showed a relationship with immune status by its correlation with myeloid-derived cell proportions in all data sets and with IL-6 measures in a prospective postpartum depression cohort." (PMID 27822318, 2016). "These markers may interact with high-sensitivity CRP and IL-6, potentially influencing both the onset and severity of postpartum depression (PPD)." (PMID 40566031, 2025). "Another study’s outcomes show that elevated serum levels of high-sensitivity C-reactive protein (Hs-CRP) and interleukin-6 (IL-6) following delivery are positively associated with EPDS scores ≥12, a threshold indicative of increased risk for postpartum depression." (PMID 40566031, 2025). "However, in studies with a bigger sample size, an increase in MDA, hsCRP, and IL-6 in the plasma of pregnant women with GDM was observed to be associated with stress and postnatal depression." (PMID 37891973, 2023). "However, the serum proinflammatory cytokines, including IL-1β and IL-6, were increased in the rats with postpartum depression." (PMID 30390665, 2018). "Both studies investigating esketamine reported a reduction in the pro-inflammatory cytokine IL-6, one in the context of labor and postpartum depression, and the other in patients undergoing elective non-cardiac thoracic surgery." (PMID 40573262, 2025).
primary open-angle glaucoma (12 papers, 2010 to 2025). "In the present study, we found that serum IL-6 levels were significantly lower in PSS patients than normal controls, suggesting that decreased serum IL-6 concentration in PSS may be associated with the characteristics of open-angle glaucoma in PSS." (PMID 28384257, 2017).
prion disease (12 papers, 2010 to 2026). A transmissible disease that is caused by a protein that is able to induce abnormal folding of normal cellular proteins, leading to characteristic spongiform brain changes, which are associated with neuronal loss without an inflammatory response. "Recent research demonstrates that BBB disruption in prion diseases can result directly from proinflammatory cytokines produced by reactive astrocytes, notably IL-6." (PMID 40331982, 2025). "Such an increase in IL-6 was observed to reduce the levels of TJ proteins in non-infected mice-isolated endothelial cells within a co-culture model, although IL-6 itself is not directly linked to prion diseases progression." (PMID 38790392, 2024). "Conversely, TNF-α, IL-4, IL-6, IL-12(p40), IL-12(p35), IL-13, and transforming growth factor-β1 are probably not pathogenic in prion disease because knockout of these cytokines did not change the disease course of prion-inoculated mice." (PMID 24219883, 2013). "AD pathways involve (IL6, AKT1 and IL1B); prion disease involves (IL6 and IL1B); and pathways of neurodegeneration-multiple diseases involve (IL6, AKT1 and IL1B)." (PMID 41601963, 2026). "This evidence identifies astrocyte-derived IL-6 as a key mediator of BBB disruption, providing valuable insight into early pathogenesis in prion diseases and highlighting astrocytes and their cytokine products as promising therapeutic targets." (PMID 40331982, 2025). "Using the ME7 model of prion disease and systemic challenge with poly I:C (12 mg/kg i.p.)we have shown an amplified expression of IFN-α and β and of the pro-inflammatory genes IL-1β and IL-6." (PMID 20399848, 2010). "Thus, although one study in mice postulated that IL-6 gene expression deficiency did not have any effect in prion pathogenesis, we strongly support the idea that this neuromodulator peptide is relevant to prion disease pathogenesis, as has been described for prion-like diseases." (PMID 33540568, 2021). "Several studies have suggested that the up-regulation of TNFα, IL1β, IL6, and COX2 plays important roles in many inflammatory diseases including cytotoxicity in brain injuries and many neurodegenerative diseases such as AD, PD, and prion diseases." (PMID 32560481, 2020).